HDAC6 (histone deacetylase 6)
Diseases named in the same sentence as HDAC6 in open-access papers (continued):
Sharing a sentence is not in itself a finding about the gene and the disease.
multiple myeloma (74 papers, 2007 to 2025). "This article reviews recent progress in the mechanisms of action of HDAC6 inhibitors for the treatment of B cell-associated hematological malignancies, such as multiple myeloma and B cell non-Hodgkin lymphoma, which are often resistant to targeted therapies." (PMID 32676030, 2020). "A fluorometric enzymatic assay was used to measure HDAC6 activity, while cell viability assay by Cell Titer Glo was used to assess the anti-tumor activity against drug-sensitive and -resistant multiple myeloma (MM) cells." (PMID 41011174, 2025). "It is not surprising that most of the studies describing the synergistic effect of HDAC6 inhibitors with bortezomib have been referred to multiple myeloma (MM) cells." (PMID 41458974, 2025). "The anti-multiple myeloma effect of HDAC6 inhibition in combinations with proteosome inhibitors is a well-established HDAC6-targeting drug combination resulting in cell death by inactivating the cell responses that deal with cytotoxic proteins." (PMID 39941046, 2025). "Ricolinostat is at the most advanced stage of development and exemplifies the promising results of selective HDAC6 inhibition regarding the safety, tolerability, and efficacy in treating blood cancers such as leukaemia, multiple myeloma, and lymphoma." (PMID 39941046, 2025). "Here, we explore the role of the ZnF-UBP binding domain of HDAC6 in the function of multiple myeloma cells." (PMID 40234445, 2025). "The effect of HDAC6 inhibitors on each proteasome catalytic activity in multiple myeloma cells was measured using peptide-based fluorescent reporters that are preferentially cleaved by the distinct catalytic sites." (PMID 38747592, 2024). "The newly discovered irreversible HDAC6 inhibitor, phenylsulfonylfuroxan-based hydroxamate 4, has superior anti-multiple myeloma activity compared to ACY-241, an HDAC6 inhibitor in clinical trials." (PMID 38584203, 2024). "As a prime example, the combination of the selective HDAC6 inhibitor ricolinostat with bortezomib demonstrated promising efficacy and safety in phase I/II trials for multiple myeloma." (PMID 39063958, 2024). "We next determined the effect of HDAC6 on pan-HLA expression on multiple myeloma cells because we had shown that HDAC6 inhibitors and HDAC6 KO increased proteasome activity." (PMID 38747592, 2024). "Because treatment of E.G7-Ova cells with HDAC6 inhibitors modulated the murine MHC-I immunopeptidome, we next determined the effect of HDAC6 inhibitors on the myeloma class I immunopeptidome." (PMID 38747592, 2024). "Future studies will address the in vivo effect of HDAC6 inhibitors on myeloma cell antigen presentation and viability." (PMID 38747592, 2024). "Using a MS-based immunopeptidomics approach, we characterized the effect of HDAC6 inhibitors on the antigenic landscape of multiple myeloma cells and identified canonical antigens and neoantigens upregulated by proteasome activation." (PMID 38747592, 2024). "HDAC6 KO in the MMCLs tested significantly increased the detection of pan HLA-A, B, C expression on multiple myeloma cells by flow cytometry." (PMID 38747592, 2024). "Among them, NP8 exhibited particularly good selective degradation of HDAC6 and inhibition of cell proliferation in multiple myeloma cells." (PMID 36770884, 2023). "Another HDAC6 inhibitor panobinostat, which is used as an anticancer drug for multiple myeloma (MM), combined with FK506 significantly affected osteoclast formation through the reduction of PPP3CA expression." (PMID 36986544, 2023). "LSD1 (lysine-specific demethylase 1) and HDAC6 selective dual inhibitors exerted synergistic effects in a xenograft model of multiple myeloma, exhibiting better effects than treatment with the single agent." (PMID 36076996, 2022). "Since inhibition of UPS by bortezomib on myeloma cells leads to aggresome formation and PS inhibits the activity of HDAC6, the combined treatment shows the synergistic effect on myeloma cells." (PMID 35802681, 2022).
multiple myeloma (continued). "Parental or bortezomib-resistant myeloma cells were treated with either ricolinostat or tubaicin, two distinct HDAC6-specific pharmacological inhibitors." (PMID 34888496, 2021). "Immunoblotting results confirmed the upregulation of HDAC6 protein expression by panobinostat in all four myeloma cell lines." (PMID 34888496, 2021). "Using ACY-1215 treatment (a selective HDAC6 inhibitor that has successfully passed a phase-Ib clinical trial for refractory multiple myeloma), we observed a significant tumor growth inhibition in xenograft models." (PMID 34345016, 2021). "HDACi with selectivity for HDAC6 has been developed and explored as single agents or components of combination therapy strategies for multiple myeloma." (PMID 34888496, 2021). "Ricolinostat, an HDAC6-selective inhibitor, was effective in models of multiple myeloma and lymphoma in vitro and in vivo." (PMID 34298787, 2021). "In particular, panobinostat caused a substantial downregulation of HDAC7 as well as a significant upregulation of HDAC6 in myeloma cells." (PMID 34888496, 2021). "It has been reported that selective HDAC6 inhibitors augmented the anti-tumor activity of pomalidomide as well as bortezomib in myeloma." (PMID 34888496, 2021). "Variation of the linker length as well as the linking position culminated in the series of compounds that were evaluated for their HDAC6 degradation effects along with efficacy in multiple myeloma." (PMID 33840388, 2021). "Further Phase I and Phase II studies investigate the effects of the HDAC6-preferential candidates ricolinostat and citarinostat on multiple myeloma and other malignancies, including solid cancers." (PMID 33562653, 2021). "Citarinostat (ACY-241) is a promising oral histone deacetylase 6 (HDAC6)-selective inhibitor currently in clinical trials for the treatment of multiple myeloma (MM) and non-small-cell lung cancer (NSCLC)." (PMID 33807514, 2021). "ACY-1215, an orally bioavailable HDAC6-selective inhibitor, had previously completed Phase 1 and 2 clinical trials for treatment of multiple myeloma." (PMID 33835029, 2021). "A deeper understanding of how overexpression and knockdown of HDAC6, 7, and 11 modulate myeloma survival and drug resistance will enable the development of more precise HDACi strategies." (PMID 34888496, 2021). "Inhibition of HDAC6 has also beneficial effects treating multiple myeloma, an expansion of malignant PCs that secrete abnormal antibodies." (PMID 31708928, 2019). "Consistently, in a study in multiple myeloma, ACY241 (an HDAC6 selective inhibitor) significantly decreases PD-L1 expression on CD138+ myeloma cells in patients." (PMID 31258527, 2019). "HDAC6 inhibitors such as ACY-1215 are currently in clinical studies for the treatment of multiple myeloma and have been found to have anti-inflammatory influences in osteoarthritis studies." (PMID 31311988, 2019). "In the present study, we investigated the anti-myeloma effect of NexA, a novel selective HDAC6 inhibitor." (PMID 30782785, 2019). "WT161, a bioavailable HDAC6 inhibitor, activates caspase and augments apoptosis in multiple myeloma." (PMID 31354911, 2019). "These interesting findings provide the rationale for the future advancement of this novel HDAC6 inhibitor as a potential therapeutic anti-myeloma agent." (PMID 30782785, 2019). "In the present study, we investigated the anti-myeloma effect of Nexturastat A (NexA), a novel selective HDAC6 inhibitor." (PMID 30782785, 2019). "These interesting findings provided the rationale for the future advancement of this novel HDAC6 inhibitor as a potential therapeutic anti-myeloma agent." (PMID 30782785, 2019). "Myc-positive neuroblastoma, KRAS-positive colorectal cancer and multiple myeloma cells showed marked cell growth inhibition in response to HDAC6 inhibitors." (PMID 30318510, 2018). "Different studies have reported an overexpression of HDAC6 in primary and cultured myeloma and lymphoma cells." (PMID 30096875, 2018).
multiple myeloma (continued). "Ricolinostat, the first-in-class HDAC6 selective inhibitor, has demonstrated good toxicity profile in patients and preliminary evidence of anti-myeloma efficacy in combination with lenalidomide and dexamethasone." (PMID 30096875, 2018). "The third molecule, ACY-1215, was chosen not only for its potency and selectivity towards HDAC6, but also because this compound is currently tested in a phase II clinical trial for multiple myeloma (clinicaltrails.gov identifier: NCT01323751)." (PMID 27957719, 2017). "RCL selectively inhibited HDAC6, induced dose-dependent cell death in several sensitive and resistant MM cell lines, and triggered synergistic myeloma cell cytotoxicity when combined with BTZ or with carfilzomib both in vitro and in vivo." (PMID 28203307, 2017). "Synergy between proteasome and HDAC inhibitors in myeloma has been documented, and at least in part is due to HDAC6 inhibition and disruption of aggresome formation." (PMID 29100294, 2017). "In hematological malignancies, HDAC6 has been reported to be overexpressed in primary and cultured multiple myeloma cells and T-cell lymphoma." (PMID 28315173, 2017). "HDACi with anti-myeloma activity in clinical development discussed in this review include vorinostat, panobinostat and selective HDAC6 inhibitor, ricolinostat." (PMID 28398261, 2017). "Ricolinostat (ACY-1215) inhibits HDAC6, resulting in tubulin hyperacetylation and interacts synergistically in combination with bortezomib and carfilzomib to treat lymphoma and multiple myeloma (MM) cells." (PMID 28315173, 2017). "ACY-241 is a novel orally available selective HDAC6 inhibitor under clinical development in combination with pomalidomide and dexamethasone in multiple myeloma (NCT 02400242)." (PMID 27926524, 2017). "RCL, a hydroxamic acid HDAC6-selective inhibitor, showed strong anti-myeloma activity when combined with BTZ or with carfilzomib in preclinical studies." (PMID 28203307, 2017). "In multiple myeloma (MM), we have shown that HDAC6 knockdown or treatment with the selective small molecule HDAC6 inhibitors tubacin, ricolinostat, and WT161, synergistically enhances bortezomib-induced cytotoxicity." (PMID 29113288, 2017). "It should also be noted that pharmacological inhibitors of HDAC6, which are used in clinical trials for the treatment of myeloma, mimic the anti-mitotic effect of FAM65B." (PMID 27556504, 2016). "Inhibition of HDAC6 in combination with proteasome inhibition results in synergistic toxicity to multiple myeloma cells due to accumulation of ubiquitinated proteins." (PMID 25915736, 2015). "Histone deacetylase 6 (HDAC6) is overexpressed in multiple myeloma cells and may be involved in the acquisition of resistance to conventional anti-proteasome treatments." (PMID 40234445, 2025). "The anti-tumor effects of two selective HDAC6 inhibitors, ricolinostat and citarinostat, have been investigated clinically as a combination-based regimen and demonstrated good response in relapsed multiple myeloma." (PMID 39800760, 2025). "Therefore, we addressed the effect of HDAC6 inhibitors on GFP-expressing multiple myeloma CD138+ cells that were seeded in a 3-D matrigel system to develop large spheroids." (PMID 38747592, 2024). "Tethering the selective HDAC6 inhibitor next-generation hydrofurotanone to a CRBN ligand resulted in a drug that could counteract the proliferation of multiple myeloma." (PMID 36770884, 2023). "In this context, a study was conducted by our research group to modify the cap construct of tubastatin (structure simplification approach) and the resulting compounds displayed excellent activity profile against multiple myeloma coupled with a striking HDAC6 inhibitory profile." (PMID 33840388, 2021). "In addition, HDACi have been shown to target blood cancer-specific pathways, such as BCL6 overexpression in B-cell lymphoma, aggresome dependency in multiple myeloma, and HDAC6 overexpression in lymphoma." (PMID 34298787, 2021).
multiple myeloma (continued). "Since HDAC6 transcript and protein expressions were increased after exposure to panobinostat in sensitive and resistant myeloma cells, we hypothesized that HDAC6 specific inhibitors might augment panobinostat efficacy." (PMID 34888496, 2021). "HDAC6-specific inhibitors are widely used in multiple myeloma, studies have shown that As2O3 plays an anti-multiple myeloma role by inhibiting the activity of HDAC6, promoting the acetylation of α-tubulin, reducing the function of Hsp90, and leading to the inactivation of NF-κB." (PMID 34530730, 2021). "Indeed, panobinostat increased the expression of HDAC6 in both SUDHL4 (a diffuse large B-cell lymphoma cell line) and Daudi (a Burkitt lymphoma cell line), suggesting the HDAC6 upregulation by panobinostat is applicable to both myeloma and lymphoma models." (PMID 34888496, 2021). "Interestingly, panobinostat treatment altered HDAC gene expression: HDAC7 was downregulated while HDAC6 was upregulated after panobinostat treatment in myeloma cell lines." (PMID 34888496, 2021). "Therefore we quantified HDAC6 transcript expression before and after vorinostat or panobinostat treatment in wildtype and bortezomib-resistant myeloma cells individually." (PMID 34888496, 2021). "In addition, we found that HDAC6 was upregulated in bortezomib-resistant myeloma cells vs. wildtype cells; however, the degree of upregulation did not achieve statistical significance." (PMID 34888496, 2021). "Ricolinostat, a selective HDAC6 inhibitor, was well tolerated and moderately effective in combination with bortezomib and the immunomodulator lenalidomide plus dexamethasone in refractory multiple myeloma." (PMID 32410999, 2020). "However, decreased Treg frequencies and FOXP3 expression upon treatment with HDAC6-selective inhibitors have also been demonstrated in models of non-small cell lung cancer and multiple myeloma." (PMID 30728070, 2019). "In addition, HDAC6 inhibition enhances tumor immunity and has been suggested to strengthen the cytotoxic effects of therapeutic antibodies against myeloma." (PMID 30987296, 2019). "However, recent studies on cancer therapy have demonstrated that HDAC6 inhibitors inhibit proliferation and induce apoptosis in multiple myeloma cells." (PMID 30453928, 2018). "Furthermore, a selective HDAC6 inhibitor with a proteasome inhibitor has been employed in multiple myeloma." (PMID 29593536, 2018). "Additionally, we also tested ACY-1215 (also known as ricolinostat), which has been demonstrated to be a potent and selective HDAC6 inhibitor in human multiple myeloma cell lines." (PMID 27957719, 2017). "Furthermore, HDAC6 has been shown to regulate the processing of misfolded proteins via the aggresome pathway, a process that is particularly important to myeloma cells which have to cope with a significant load of unfolded immunoglobulin." (PMID 26015393, 2015). "Importantly, there are small molecule inhibitors for HDAC6 currently being tested in advanced clinical trials for other tumor types (myeloma and lymphoid malignancies)." (PMID 26643555, 2015). "Tubacin, a small molecule inhibitor of HDAC6, prevents deacetylation of α-tubulin and produces accumulation of polyubiquitinated proteins and apoptosis, and further acts synergistically with BZ to induce cytotoxicity in multiple myeloma." (PMID 22200786, 2012). "Although As2O3 has been extensively studied as potential anti-myeloma treatment, the precise functions of As2O3 in the myeloma cells remain to be defined; especially whether As2O3 could affect activity in HDAC6-Hsp90-IKKα-NFκB signaling axis." (PMID 22384180, 2012). "Therefore, our studies provide an important insight into the molecular mechanism of anti-myeloma activity of As2O3 in HDAC6-Hsp90-IKKα-NFκB signaling axis and the rationale for As2O3 can be extended readily using all the HDAC associated diseases." (PMID 22384180, 2012).
multiple myeloma (continued). "Taken together, our results of HDAC6-dependent As2O3 action may also be mediated through arrest cell motility with Hsp90, which has already emerged as a promising class of anti-cancer drugs in myeloma." (PMID 22384180, 2012). "We assume that HDAC6-dependent α-tubulin acetylation contributes to the decreased cell motility and invasive migration of myeloma cells; thus, this action of the As2O3-induced α-tubulin acetylation could be one of the reasons for As2O3 in myeloma treatment." (PMID 22384180, 2012). "We have shown that HDAC6 inhibitors stimulate proteasomes to amplify and expand MHC-I antigen presentation on myeloma cells and promote cytotoxic T-cell responses." (PMID 38747592, 2024). "Treatment of multiple myeloma (MM) cells with a panel of FDA-approved and investigational HDAC6 inhibitors dramatically increased MHC-I antigen presentation and significantly enhanced the antimyeloma activity of healthy and patient-derived autologous T-cells." (PMID 38067336, 2023). "HDAC6 and HDAC7 protein expression was probed to determine if transcript changes were seen at the protein level in bortezomib-resistant myeloma cells." (PMID 34888496, 2021). "Surprisingly, we discovered HDAC6 and HDAC7 were upregulated and downregulated, respectively, in two separate models of bortezomib-resistant myeloma cells." (PMID 34888496, 2021). "In multiple myeloma, sensitivity to JQ1 is increased after cotreatment with HDAC6 inhibitor as confirmed through cell proliferation inhibition and apoptosis promotion." (PMID 32961679, 2020). "HDAC6-selective inhibitors C1A and ACY-1215 were potent in multiple myeloma cell lines (ARH77, JJN3, KMS12, U266, RPMI8226, KMS11, OPM-2) with a mean GI50 of 0.48 and 1.04, respectively." (PMID 30318510, 2018). "In multiple myeloma, ACY-1215 has a specific inhibitory effect on HDAC6 activity: even a very low dose can induce potent acetylation of α-tubulin, but triggering the acetylation of lysine on histone H3 and histone H4 needs higher doses." (PMID 30050135, 2018). "We have shown that WT-161, a histone deacetylase 6 (HDAC6) inhibitor, shows remarkable anti-tumor activity in multiple myeloma (MM) in preclinical models." (PMID 29113288, 2017). "Currently, two isoform-specific HDAC6 inhibitors, ricolinostat (ACY-1215) and ACY-241 are under phase I/II clinical evaluation for the treatment of patients with multiple myeloma and lymphoid malignancies." (PMID 29179471, 2017). "There was no determinable effect of CHR-3996 on the levels of acetylated α-tubulin or ubiquitinated proteins in myeloma cell lines H929 and RPMI-8226, indicating low activity of this compound against HDAC6." (PMID 26015393, 2015). "JIB-097 is a dual LSD1 and histone deacetylase 6 (HDAC6) inhibitor, which was tested against various cancer types, e.g., in multiple myeloma MM1.S cells-derived mice xenograft, and its combination with bortezomib or pomalidomide enhanced tumor volume reduction." (PMID 40940894, 2025). "The effect of HDAC6 inhibitors on cell viability, proteasome activity, and pan-MHC-I antigen presentation was determined using CD138+ cells isolated from the bone marrow of patients with multiple myeloma with treatment-refractory disease." (PMID 38747592, 2024). "For instance, ACY-1215 (ricolinostat), a specific HDAC6 inhibitor, is undergoing a phase 1b trial for relapsed/refractory multiple myeloma, while ACY-241, a second-generation HDAC6 inhibitor with improved properties, is being investigated for multiple myeloma treatment." (PMID 37660065, 2023). "Our data also revealed that panobinostat but not vorinostat upregulated HDAC6 expression in myeloma cells." (PMID 34888496, 2021). "In multiple myeloma cell lines, the pan-HDACi panobinostat has demonstrated the capacity to markedly upregulate PD-L1 by enhancing STAT1 expression in the presence of IFN-γ, while the HDAC6-selective inhibitor A452 was shown to induce PD-L1 upregulation in multiple myeloma cells in vitro." (PMID 38672128, 2024).